PHC1P1 (polyhomeotic homolog 1 pseudogene 1)
Synonyms: formerly PHC1B
Gene: Processed pseudogene on chromosome 12 (55,411,727 to 55,414,787, reverse strand). Ensembl gene ENSG00000179899.
Diseases named in the same sentence as PHC1P1 in open-access papers:
PHC1P1 is named in the same sentence as 1 disease in open-access papers, as found by Europe PMC text mining. Sharing a sentence is not in itself a finding about the gene and the disease. The quoted sentences say what the papers report.
tumor (1 paper, 2022). "Except for AC241952.1 and PHC1P1, the expression levels of other predicted pseudogenes were significantly higher in tumor tissues than in normal tissues (P < 0.05)." (PMID 36447214, 2022). "Univariate Cox regression analysis of clinical indicators revealed that T stage, N stage, M stage, pathologic stage, age, histological type, residual tumor, HSPA8P4, PHC1P1, RBMS1P1, LINC01303, and MSC-AS1 were meaningful, and the expression level of COL5A2 was also significant." (PMID 36447214, 2022).